CDK4 (cyclin dependent kinase 4)
Diseases named in the same sentence as CDK4 in open-access papers (continued):
Sharing a sentence is not in itself a finding about the gene and the disease.
cancer (continued). "CDK4 targeted therapy can inhibit the G1S progression and has been shown to control cancer development." (PMID 33036243, 2020). "Palbociclib, an FDA approved drug established to target CDK4/6, has been evaluated in ∼30 different cancer indications." (PMID 32413516, 2020). "The efficacy of CDK4/6 inhibitors relies on the presence of wild-type RB1 in the cancer cells as inhibition of CDK4/6 blocks proliferation through the accumulation of hypo-phosphorylated RB1." (PMID 32344731, 2020). "Given the increasing number of usage for CDK4/6 inhibitors in cancer treatment and the potential of cyclin E-CDK2 mediated drug resistance, our study also has therapeutic relevance." (PMID 33082317, 2020). "Combination therapy has been shown to achieve higher efficacy; such as the combination of HT with mTOR inhibitors or CDK4/6 inhibitors are used for tumors with enhanced mTOR signaling and for CDK4/6 sensitive cancer, respectively." (PMID 32545494, 2020). "Whereas many of the recommendations for cancer treatment relate to cytotoxic chemotherapy, guidance on newer therapies, e.g., immune checkpoint CDK4/6, mTOR, and PARP inhibitors, appears only intermittently." (PMID 33330049, 2020). "The successful example indicated that it was feasible to regard CDK4 as a drug target to restrain cancer development." (PMID 33009370, 2020). "We further show that elevated CDK4 expression is a favorable prognostic index for cancer patients instead of high CDK6 expression that is close to poor prognosis." (PMID 33282875, 2020). "The purpose of the present study was to estimate the prevalence of CDK4/6 inhibitors use among the cancer patients from the MRONJ cohort of the University of Messina." (PMID 33353034, 2020). "Typically, P15 and P16 serve as the primary negative regulators of CDK4/6, yet in human cancers, overexpression of P18 has been shown to compensate for loss of P15 and/or P1624." (PMID 32111816, 2020). "CDK4/6 can trigger G1 entry from quiescence and facilitate G1 progression by combining with cyclin D1 and then promoting cancer cell proliferation." (PMID 32227572, 2020). "For example, experiments can be carefully designed to investigate the effect of CDK4/CDK6 inhibitors in treating Subtype_2 cancer patients using in vitro cancer cell line model, ex vivo or in vivo cancer models." (PMID 33344220, 2020). "Despite overlapping functions in cell cycle regulation, CDK4 and CDK6 dysregulation is linked to different cancer types." (PMID 33255177, 2020). "Accordingly, inhibition of insulin, IGF-1, and leptin by fasting can co-operate with blockade of estrogen and CDK4/6 to abrogate cancer cell proliferation and survival." (PMID 33271979, 2020). "Compared with CDK4 depletion alone, combined depletion induced apoptosis in cancer cells in a dose-dependent manner." (PMID 31899991, 2020). "For this reason, tumor with high levels of p16ink4a, like human papilloma virus-positive cancers (e.g., cervical cancer and squamous cell cancer of the head and neck district), would be resistant to CDK4/6 inhibitors." (PMID 31450618, 2019). "CDK4/6 inhibitors show significant clinical efficacy in cancer treatment by targeting the central G1/S transition machinery." (PMID 31253784, 2019). "Components of the CDK4/6 pathway are often dysregulated in cancer making this complex a promising target for treatment." (PMID 31235824, 2019). "CDK4 and CDK6 have been implicated as drivers of oncogenesis in several cancers for more than 20 years." (PMID 31480389, 2019). "Recently, studies showed that AMPK activation induced G0/G1 phase arrest by decreasing expression of cyclin D1 and CDK4 in diverse cancer cells." (PMID 31887988, 2019). "Of note, the chief mechanism accounting for the efficacy of CDK4/6 inhibitors as anti-cancer drugs is cellular senescence." (PMID 31653055, 2019). "Palbociclib is a selective inhibitor of cyclin-dependent kinases 4 and 6 (CDK4/6) approved for the treatment of some cancers." (PMID 30692638, 2019).
cancer (continued). "Another tumour suppressor gene, p16, encodes a specific inhibitor of CDK4 and CDK6 and is altered in a wide range of human cancers." (PMID 30668541, 2019). "Cyclin-dependent kinase 4 (CKD4) is highly expressed in human cancer, and palbociclib, the inhibitor of CDK4 has been used clinically under FDA approval for application in cancer therapeutic remedies." (PMID 30808351, 2019). "As reported for cancer cells and demonstrated by our data, this small-molecule inhibitor exhibits strong selectivity for CDK4 and CDK6 with potent anti-proliferative effects." (PMID 31101827, 2019). "This study demonstrates that P16 methylation can increase the sensitivity of cancer cells to the CDK4/6 inhibitor palbociclib." (PMID 31652270, 2019). "Cancer-specific mutations, such as those affecting receptor tyrosine kinases (RTKs), or RAS, RAF, PI3K, or PTEN mutations, can enhance cyclin D-dependent CDK4/6 activity." (PMID 31450618, 2019). "For instance, palbociclib (PD0332991) is a potent and selective CDK4/6 inhibitor used for the treatment of specific cancers." (PMID 31039152, 2019). "Similar to other targeted cancer therapies, a prominent issue with CDK4/6 inhibition is drug resistance." (PMID 30890123, 2019). "The highly specific CDK4/6 inhibitors have, however, demonstrated pro-apoptotic effects in other cancer types." (PMID 30720718, 2019). "It has been reported that miR-124 inhibits proliferation in cancer cells through targeting CDK4, CBL, Slug and androgen receptor." (PMID 31367191, 2019). "This is concordant with the recent reports on the synergistic anti-cancer activity of combined CDK4/6 and mTOR targeting." (PMID 31388935, 2019). "Our data demonstrate that cyclin D1 deficiency is a druggable vulnerability of SCCOHT, providing a rationale for a clinical trial using the available CDK4/6 inhibitors to treat this often-fatal cancer of young women." (PMID 30718512, 2019). "An in vitro systematic substrate screen in several cancer-derived cells lines concluded that CDK4/6 can phosphorylate and stabilize FOXM1 to promote entry into the S phase of the cell cycle." (PMID 30978209, 2019). "YAP is involved in resistance to a variety of chemotherapeutic drugs in several cancer types, including molecular targeted drugs such as inhibitors of CDK4/6, EGFR and BRAF, as well as classical cytotoxic drugs such as 5-FU, cisplatin (CDDP) and doxorubicin." (PMID 31540262, 2019). "Consistent with circadian regulation, a CDK4/6 inhibitor approved for cancer treatment reduced growth of cultured cells and mouse tumors in a time-of-day–specific manner." (PMID 31039152, 2019). "Selective CDK4/6 inhibitors provide a novel therapeutic approach for patients with malignant tumors." (PMID 31787897, 2019). "Accumulating evidence also suggests that mutations of the CCND1 gene that result in nuclear retention and constitutive activation of CDK4/6 kinases are oncogenic drivers in cancer." (PMID 29969496, 2018). "In line with this, deregulation of CDKs are common hallmarks in cell-cycle alterations found in tumors, and CDK4/6 has a pivotal role in the G1-to-S-phase cell-cycle transition in cancer." (PMID 29063134, 2018). "Palbociclib inhibits the binding of CDK4/6 to D type cyclins and has been developed as a promising therapeutic for cancers with altered function of the Cyclin D‐CDK4/6‐p16INK4a pathway." (PMID 29744983, 2018). "In particular, CDK4/6 inhibitors seem to present suitable targets in a majority of patients with advanced cancer." (PMID 30322180, 2018).
cancer (continued). "Another limitation in using the combinatory treatment (CDK4/6 inhibitors and DNA damaging agents) is the deficiency of RB1 in some primary cancer cells, which has been linked to poor prognosis and altered response to anticancer treatment." (PMID 29306194, 2018). "Consistently, CDK4/6 inhibitors have been shown to be effective against HER2+ cancers in animal models." (PMID 29669860, 2018). "Loss of CDKN2A is known to correlate with poor outcome in ccRCC, PRCC, and other cancer types, but this demonstrates that it is a universal feature of RCC and is potentially targetable with CDK4/6 inhibitors that target the downstream effects of p16 loss." (PMID 29617669, 2018). "The discovery of the role of CDK 4/6 in cell cycle progression and development of inhibitors allowed scientists to investigate the effects of CDK4/6 inhibitors in fast-proliferating cancer cells." (PMID 29306194, 2018). "The studies on the relevance of cell cycle in cancer point out deregulation of p21 and CDKs (CDK4 and CDK6)." (PMID 29426343, 2018). "CDK4, a cancer gene 10 Mb proximal to MDM2 in both human and canine genomes and often the target of bipartite amplification alongside MDM2, was co-amplified in three of these cases." (PMID 30188888, 2018). "PARP1 deficiency, resulting from administration of CDK4/6 inhibitors, impairs OGG1-dependent BER and sensitizes cancer cells to oxidative imbalance-induced death." (PMID 29306194, 2018). "On the other hand, phosphorylation of retinoblastoma protein 1 (RB1) carried out by CDK4/6 is pivotal in the transition from G1 to S phase in many cancer cells." (PMID 30002440, 2018). "It is active in cancers harboring aberrations that increase Cdk4/6 activity e.g. cyclin D1 translocation." (PMID 29789630, 2018). "CDK4 was amplified frequently in several cancers and was considered to be essential for the initiation of cell cycle." (PMID 30216655, 2018). "Accumulating evidence suggests that mutations of the CCND1 gene that result in nuclear retention and constitutive activation of CDK4/6 kinases are oncogenic drivers in cancer." (PMID 29969496, 2018). "The cyclin-dependent kinase 4/6-retinoblastoma protein (CDK4/6-Rb) pathway of cell cycle control is known to be aberrant in a large proportion of cancers." (PMID 29670090, 2018). "In keeping with this critical role, small molecule CDK4 inhibitors (CDK4i) have shown considerable promise as anti-cancer agents and are currently in phase I/II clinical trials in a variety of malignancies." (PMID 30301139, 2018). "Numerous studies have shown that CDK4/6 are aberrantly active in many different forms of human cancers, largely due to high levels of cyclin D, an important cofactor for CDK4/633." (PMID 30518851, 2018). "Intact Rb is critical to the mechanism of CDK4/6 inhibition in cancer treatment, and CDKN2A loss with intact Rb mechanistically predicts sensitivity to CDK4/6 inhibitors." (PMID 30293995, 2018). "As one of the most important proteins to regulate cell cycle, Cyclin D1 can activate CDK4, which allows the cell cycle to progress through G1 into S, thus promoting the development of various cancers." (PMID 29422775, 2018). "Early evidence indicating Cyclin D/CDK4 as an oncogene has stimulated research into the development of small-molecule CDK inhibitors as cancer therapeutics." (PMID 30428574, 2018). "Cell cycle inhibition with targeted CDK4/6 inhibitors is a new therapeutic approach showing promise as a maintenance therapy in cancer." (PMID 29644000, 2018). "Palbociclib is an orally administered inhibitor of cyclin-dependent kinases 4 and 6 (CDK4/6), enzymes that promote entry into the cell cycle and become dysregulated in many cancers (Asghar, Witkiewicz, Turner, & Knudsen, 2015)." (PMID 30564467, 2018).
cancer (continued). "This compound is a CDK4/CDK6 inhibitor that efficiently induces senescence in responsive cancer cells." (PMID 30012580, 2018). "Of note, the CDK4 pathway is frequently deregulated in several cancers, including PDAC, with the p16INK4A tumour suppressor inactivated in 80–90% of clinical specimens." (PMID 30428574, 2018). "Since its activity plays a crucial role in the proliferation and progression of cancer, pharmacological inhibitors targeting the CDK4/6 pathway have emerged as an attractive approach in oncology." (PMID 29670090, 2018). "Disruption of the PRMT5/CDK4 interaction revealed PRMT5 knockdown HepG2 cells to be more sensitive to the CDK4 inhibitor fascaplysin, marking the combination of PRMT5 and CDK4 inhibition as a potential cancer therapy." (PMID 29568320, 2018). "We observe that a few gene pairs have substantial evidence across all cancer types (e.g., CDK4 and CDK2 pair)." (PMID 30514202, 2018). "DM chromosomes have a predisposition to involve cancer oncogenes such as MYC proto-oncogene protein (MYC), MDM2 proto-oncogene (MDM2) or cyclin-dependent kinase 4 (CDK4)." (PMID 29616301, 2018). "Abemaciclib, a CDK4 inhibitor, have shown efficacy in various xenograft models for human cancer including NSCLC." (PMID 29464099, 2018). "Previous findings suggested that the deregulation of CyclinD1 expression and CDK4 activation directly lead to some cancer hallmarks by inducing proliferation." (PMID 29178939, 2017). "CDK4/6-Cyclin D pathway is often deregulated in cancer; therefore specific inhibitors have been developed." (PMID 28653662, 2017). "Palbociclib is a specific CDK4/6 inhibitor, which decreases the phosphorylation of RB and subsequently inhibits cancer cell growth." (PMID 29261702, 2017). "In Rb-pathway, p16 not only mediates cell cycle progression through blocking CDK4/ cyclin D1 activity, but also show as a factor maintaining cisplatin resistance in cancer cells." (PMID 29254192, 2017). "As such, CDK4/6 appears to be a key enzyme necessary for the proliferation of human cancers that have functional RB." (PMID 28418845, 2017). "Fascaplysin has been reported to exert an anti-cancer effect through the inhibition of CDK4 activity." (PMID 28961193, 2017). "In consideration of the pivotal role of CDK4/6 in cell cycle progression, amounting studies have been conducted to suppress cancer cell proliferation through targeting the CDK4/6 signaling for effective cancer therapies during the past decades." (PMID 28438180, 2017). "The western blot data indicated that CDK4 protein was significantly downregulated in tumors derived from miR-1 overexpressing cancer cells compared with that in the controls." (PMID 28159933, 2017). "Immunohistochemistry confirmed a higher expression for cyclin D1 and CDK4 proteins in cancer samples." (PMID 28852180, 2017). "The association between CDKN2A/B deletion and the sensitivity to palbociclib, an FDA-approved CDK4/6 inhibitor, has been demonstrated in many cancers." (PMID 29089060, 2017). "The abundance of mechanisms by which transformed cells can deregulate CDK4/6 activity suggests this enzyme is crucial for cancer pathogenesis and inhibiting CDK4/6 activity has the potential to be therapeutically beneficial." (PMID 28418845, 2017). "As such, specific metabolic reprogramming events in response to CDK4/6 depletion or inhibition appear to be conserved among cancer cells of different origin." (PMID 28978620, 2017). "A further potential cancer cell vulnerability inferred from our analysis was a compromised adaptation to hypoxia as a consequence of CDK4/6 knockdown." (PMID 28978620, 2017). "Herein, we have undertaken a systematic study of the consequences on central carbon metabolism of the depletion or inhibition of CDK4/6 in cancer cells." (PMID 28978620, 2017).
cancer (continued). "Previous studies have shown the anti-cancer effect of fascaplysin through the suppression of CDK4 and cell cycle progression in various cancer cells, but the precise molecular mechanism by which fascaplysin attenuates cancer cell growth remained unexplored." (PMID 28961193, 2017). "Here, for the first time, we examined the dependence of the CDK4-RB axis in the anti-cancer effect of fascaplysin." (PMID 28961193, 2017). "There are numerous ways in which cancers with functional RB enhance CDK4/6 activity allowing for deregulated proliferation." (PMID 28418845, 2017). "With regard to the mechanism of action of the ObR antagonists, we showed that, in non-cancer HGrC1 cells, Lan1 and Lan2 decreased the expression of cyclin A2 and cdk4." (PMID 28861689, 2017). "Through their binding to cdk2 and cdk4, p21 and p27 have been reported to induce blockade of G1/S transitions of cell cycle and then premature senescence in cancer cells." (PMID 28289384, 2017). "Deregulation of the cell cycle checkpoint proteins, such as cyclin-dependent kinases CDK4 and CDK6, is a key hallmark of cancer, resulting in uncontrolled cellular proliferation and tumorigenesis." (PMID 28653662, 2017). "Cyclin D1 and CDK4 are key cell cycle proteins, and have been found to be overexpressed in several types of human cancer." (PMID 28591705, 2017). "In particular, cyclin‐dependent kinases 4 and 6 (CDK4/6) have been studied as therapeutic targets in cancer due to their essential role in the regulation of cell cycle progression at the G1 restriction point." (PMID 28978620, 2017). "CDKN2A/B protein products restrict cell-cycle progression by inhibiting CDK4/6 kinase activity, and aberrations in these genes lead to cancer progression by dysregulation of the cell cycle." (PMID 29089060, 2017). "A third major phenotype induced by inhibition of CDK4/6 in our cancer cell models is a limited response to hypoxia accompanied with downregulation of HIF‐1α, which can also be explained by the accumulation of MYC." (PMID 28978620, 2017). "Fascaplysin is isolated from marine sponges and exerts anti-cancer effects, including the suppression of growth, angiogenesis, and metastasis in several cancer cells, through inhibition of cyclin-dependent kinase 4 (CDK4)." (PMID 29295560, 2017). "Because of a lack of therapeutically efficacious MYC inhibitors, we propose the inhibition of MYC downstream targets, in particular GLS1, as an effective strategy to overcome acquired tolerance and resistance of cancer cells to CDK4/6 inhibitors." (PMID 28978620, 2017). "We find that cancer-associated p16INK4a mutations differ in their modes of action toward CDK4 and CDK6 and in their abilities to displace CDK4 and CDK6 from Cdc37." (PMID 29091774, 2017). "As CDK4/6 inhibitors are successfully used in cancer patients, our findings can be immediately transferred to the clinic to improve the outcome of EOC patients." (PMID 28778953, 2017). "Recently, the potential therapeutic application of CDK4/6 inhibitors in a range of cancers has been considered." (PMID 28286417, 2017). "We report here that cancer cells activate autophagy in response to palbociclib, and that blockade of autophagy significantly improves the efficacy of CDK4/6 inhibition in vitro and in vivo in cancers with an intact G1/S transition." (PMID 28653662, 2017). "The method’s utility is highlighted by some well-known cancer genes such as CDK4, APC and EZH2 are only captured by GAP." (PMID 27296290, 2016). "Cyclin D1 and CDK4 are important regulatory proteins in cell growth and are overexpressed in many cancer cells." (PMID 27670681, 2016). "As a result of above, the relationship between miR-486-5p and CDK4 is greatly beneficial to the treatments of cancers through interacting with other miRNAs and genes, and it is valuable to make further studies concerned with miR-486-5p or CDK4." (PMID 27049724, 2016).